HIF1A (hypoxia inducible factor 1 subunit alpha)
Diseases named in the same sentence as HIF1A in open-access papers (continued):
Sharing a sentence is not in itself a finding about the gene and the disease.
breast cancer (continued). "These nanobubbles have exhibited the ability not only to inhibit HiF-1α expression but also to substantially reduce hypoxia-induced resistance to radiation in various cancer cell lines, such as EBC-1 and MDA-MB-231 cells (human lung and breast cancer cells)." (PMID 38063756, 2023). "In hypoxia, miR-210 and miR-373 are upregulated in HIF1A-positive breast cancer cells but not in HIF1A knockdown cells." (PMID 36835100, 2023). "Additionally, a research revealed that hypoxia stimulated HIF-1α and HIF-2α-dependent expression of AlkB homolog 5, which can demethylate Nanog mRNA and increase breast cancer stem cells." (PMID 37143105, 2023). "Also, it has been shown that overexpression of miR-210 is induced by hypoxia in a HIF-1α– and von Hippel-Lindau (VHL)-dependent manner and its expression levels are an independent prognostic factor in breast cancer samples." (PMID 36765409, 2023). "Even though not at great extents, the increase in HIF-1a expression was mainly detected when incubating the breast cancer cells with DFO." (PMID 37559137, 2023). "Further evidence of oxidative regulation of PHD2 comes from Briggs and colleagues, who found that cysteine depletion (induced by paracrine secretion of glutamate) in breast cancer cells led to oxidative inactivation of PHD and stabilization of HIF-1α during normoxia." (PMID 36935009, 2023). "A study on epigenetic modification patterns in breast cancer have revealed that HIF-1α transcription was silenced by the non-CpG methylation in the promoter." (PMID 37047150, 2023). "Palbociclib, a CDK4/6 inhibitor, can suppress HIF-1α and GLUT1 expression, and the combination with BYL719, BKM120, and BEZ235 (PI3K/mTOR inhibitors) can boost synergistic anti-proliferative and pro-apoptotic effects in breast cancer cells and a mouse model." (PMID 37460927, 2023). "In contrast, luminal breast cancer patients without recurrence had no detectable HIF1α in plasma circulating sEVs." (PMID 36892943, 2023). "Additionally, combining anti-PD-1 with reducing HIF1A concentrations by pharmacologically inhibiting Axl decreases the main tumour and metastatic loads in a preclinical model of HER2+ breast cancer, indicating a viable treatment strategy in BC." (PMID 36816977, 2023). "Clearly, HIF-1α stabilization alone does not serve as a surrogate biomarker for the complex hypoxia in breast cancer patients or models." (PMID 36057753, 2022). "It has been reported that HIF1A is a direct mRNA target of miR-34a-5p, and overexpression of miR-34a-5p downregulates HIF1α and other epithelial-to-mesenchymal transition (EMT) markers, consequently inhibiting VEGFR signaling in breast cancer." (PMID 35328346, 2022). "Hence, we first investigated if HIF-1α is expressed and stabilized in our model of MCF-7 breast cancer cells upon hypoxic stress induced chemically using cobalt chloride (CoCl2) or growing cells in hypoxic environment (1% O2) for 24 h." (PMID 35436985, 2022). "Furthermore, in a rescue experiment in MCF7 breast cancer cells, the upregulation of WWOX suppressed HIF1α target gene expression." (PMID 36271927, 2022). "Mechanistically, chemotherapeutic agents increase ACE2 expression in breast cancer cells by inducing intracellular ROS production, and increased ROS levels enhance AKT phosphorylation and subsequently increase HIF-1α expression, which in turn upregulates ACE2 expression." (PMID 36335375, 2022). "Moreover, the expression of PD-L1, pY-STAT3, HIF-1α, and LDH-A was higher in breast cancer tissue compared with normal tissue." (PMID 35927628, 2022). "According to previous studies in the literature, it was found that HIF contains two key factors, HIF-1α and HIF-2α, which can activate the transcriptional expression of m6A demethylase ALKBH5 gene at the transcriptional level in the development of breast cancer." (PMID 35733918, 2022).
breast cancer (continued). "To determine whether AKT activity is required for chemotherapeutic drug-induced expression of HIF-1α and ACE2, we first treated parental breast cancer cells with the AKT inhibitor MK-2206 to determine the expression of AKT and HIF-1α and ACE2." (PMID 36335375, 2022). "Moreover, GPx2 KD resulted in abnormal intratumoral vessels that were long and tortuous, which were consistent with HIF1α and VEGFA up-regulation in GPx2 KD in mammary tumors." (PMID 35193955, 2022). "It has been demonstrated experimentally that aminoflavone inhibits HIF-1α transcriptional activity and protein accumulation in breast cancer cell lines, and the inhibitory effect of AF on HIF-1α is independent of AhR function." (PMID 36139386, 2022). "In our study, it was discovered that BHLHE41 overexpression largely enhanced the levels of BHLHE41 and E-cadherin but repressed the levels of HIF-1α, N-cadherin, vimentin, and MMP9 in hypoxia-induced CC cells, which was consistent with the report of BHLHE41 in breast cancer." (PMID 35615737, 2022). "In addition, the present findings indicate that targeting HIF1α or its downstream effectors may represent alternative clinical targets in breast cancer, and further highlight the possibility that these approaches may also be effective on cells at very initial stages of breast cancer formation." (PMID 34294889, 2022). "Moreover, HIF-1α promoted lymphatic metastasis of hypoxic breast cancer cells by activating PDGF-B transcription, while an AKT/HIF-1α/PDGF-BB autocrine loop mediates hypoxia-induced chemoresistance in liver cancer cells." (PMID 35158804, 2022). "However, in breast cancer cells, we found that miR-101 can target and down-regulate VHL expression, which is a negative regulator of hypoxia-inducible factor 1 subunit alpha (HIF1α) to increase HIF-1α expression and HIF-1α downstream target VEGFA expression." (PMID 36497343, 2022). "Indeed, in breast cancer cell line (MDA-MB-231), the inhibition of HIF-1α expression using cardamonin repressed the mechanistic target of rapamycin (MTOR) pathway causing increased OXPHOS activity and enhanced ROS, which finally led to apoptosis." (PMID 35205167, 2022). "HIF-1α positivity, thus, has a negative correlation to the distribution of ER expression in the breast cancer subtypes." (PMID 35140341, 2022). "However, the details of the regulation between HIF-1α and RRM2 still need further study in breast cancer." (PMID 36678539, 2022). "Consistently, breast cancer tissues that were CD44+CD24− had higher levels of HIF-2α (not HIF-1α), suggesting that patients with higher level of HIF-2α are likely to have a higher percentage of stem-like cells in their cancer tissues." (PMID 35301432, 2022). "In this study, we demonstrated that NDRG1-OT1 was upregulated under hypoxia in different breast cancer cell lines by HIF-1α, but not HIF-2α." (PMID 36127332, 2022). "In response to hypoxia, hypoxia-inducible factor (HIF)-1α and HIF-2α were stimulated to promote ALKBH5 expression in breast cancer cells; subsequently, ALKBH5 inhibited the m6A level in the 3′UTR of Nanog mRNA and increased NANOG expression, resulting in enhanced breast cancer stem cell phenotype." (PMID 35859892, 2022). "Moreover, the engagement of PI3K/AKT and MAPK by IGF-I signaling stimulated HIF-1α and its target genes GPER and VEGF-A in breast cancer cells and CAFs and promoted tumor angiogenesis." (PMID 35158804, 2022). "Similarly, in human breast cancer, the reduction in the expression of SIRT3 results in upregulation of the HIF-1α target genes." (PMID 35897717, 2022). "Additionally, in vivo experiments confirm this observation by proving that inhibiting HIF-1α, P4HA1, or P4HA2 in orthotopic tumors, developed via injection of human breast cancer cells into immunodeficient mice, decreases tissue stiffness and fibrosis." (PMID 36140753, 2022).
breast cancer (continued). "In addition, sinomenine notably elevated the levels of miR-340-5p in breast cancer SP cells exposed to hypoxia and reduced the expression of SIAH2 and HIF-1α." (PMID 35309179, 2022). "Unlike with the upregulation of SIAH2 and HIF-1α induced by hypoxia, miR-340-5p was decreased by hypoxia in breast cancer SP cells." (PMID 35309179, 2022). "However, under normoxia and hypoxia conditions, both ERα and HIF-1α regulate histone demethylase JMJD2B and orchestrate breast cancer cell growth by epigenetically regulating the genes implicated in the cell cycle." (PMID 36185256, 2022). "To further investigate the combined efficacy of targeting HIF-1α during anti–CTLA-4 therapy, we performed similar drug-treatment experiments using immunocompetent C57BL/6 recipients and the E0771 breast cancer or MC38 colon adenocarcinoma model and observed synergistic effects in all models." (PMID 35239514, 2022). "Therefore, DLEU1, by acting as a coactivator for HIF-1α, up-regulates CKAP2 expression and promotes malignancy of breast cancer." (PMID 35853854, 2022). "Furthermore, ENO1 promotes the proliferation and metastasis of breast cancer cells through the PI3K/AKT pathway, and in turn is upregulated by HIF1α." (PMID 35443744, 2022). "To test this hypothesis, we explored the interactions between DLEU1, HIF-1α, and CKAP2 in breast cancer tissues acquired from patients or database, in breast cancer cells cultured in vitro, and in in vivo xenografts or metastasis models." (PMID 35853854, 2022). "However, compared with that in wild-type breast cancer cells, HNK had a weaker inhibitory effect on these genes in breast cancer cells overexpressing HIF-1α." (PMID 35350760, 2022). "Consistent with the assumption that the hypoxic state increases the resistance of breast cancer cells to DOX and the hypoxic state itself induces HIF-1α overexpression, targeting HIF-1α may overcome therapeutic resistance." (PMID 36613834, 2022). "A study on breast cancer cell lines, 4T1 and MDA-MB-231, showed that mitochondrial malic enzyme 2 might decrease the level of α-ketoglutarate, leading to HIF-1α stabilization." (PMID 36139678, 2022). "The expression of ACE2 and HIF-1α in parental and drug-resistant breast cancer cells under normoxic and hypoxic conditions was analyzed by Western blot and qRT-PCR methods." (PMID 36335375, 2022). "We used an online database (ChIPBase v2.0) to predict the transcription factors for ZNF582-AS1, chr19:56, 393, 312-56, and 414, 800 (GRCh38/hg38), and the online tool suggested five potential candidates in breast cancer cell lines, namely CTCF, KDM5B, HIF1A, ARNT, and NRF1." (PMID 35681777, 2022). "Compared with control group, the WST-1 test showed that HNK had a significant cytotoxic activity against these breast cancer cells; However, in HIF-1α overexpression cells, the inhibitory effect of HNK on cell viability was weaker than that of control breast cancer cells." (PMID 35350760, 2022). "In contrast to our initial hypothesis, we show that breast cancer patients benefit from postoperative RT regarding IBTR, and any recurrence, also when the primary tumour was HIF-1α IHC positive or had high expression of hypoxic gene signatures." (PMID 35140341, 2022). "Curcumin pretreatment in the radiation-exposed breast cancer MCF-7 and MDA-MB-231 cell-derived mammosphere demonstrated increased apoptosis and reactive oxygen species formation, G0/G1 phase cell cycle arrest, and decreased HIF-1α and HSP90 protein expression." (PMID 35740529, 2022). "We found that HNK significantly downregulated HIF-1α protein levels in breast cancer cells but had no evident inhibitory effect on its mRNA." (PMID 35350760, 2022). "Similarly, to our results, the simultaneous upregulation of HIF-1α and MMP-9 was described in tumor tissues from patients with breast cancer." (PMID 33920263, 2021).
breast cancer (continued). "Our results propose that SGLT1 not only facilities a highly glycolytic phenotype, which supports the tamoxifen resistance of breast cancer cells, but also that the metabolic byproduct, lactic acid, participates in the M2-like TAM polarization in the TME, activating the HIF-1α/STAT pathway." (PMID 34006822, 2021). "To test this hypothesis, we used breast cancer cell lines (MCF-7 and MDA-MB-231), and we analyzed the expression of HIF-1α, PDK1, PDH, SIRT1, SIRT3, and ROS for mitochondrial metabolic pathway." (PMID 34771733, 2021). "Taken together, these data suggested that hypoxia-responsive long non-coding MALAT1 could be transcriptionally activated by HIF-1α and HIF-2α, act as a miRNA sponge of miR-3064-5p, and promote tumor growth and migration in breast cancer cells." (PMID 34012919, 2021). "It was found in a model with breast cancer cells that circular RNA circRNF20 promotes the Warburg effect by harboring miR-487a and, thus, allows the HIF-1a-dependent expression of HK2 via the circRNF20/miR-487a/HIF-1α/HK2 axis." (PMID 33806538, 2021). "Despite the decrease in CA IX and CA XII protein levels after treatment with 13b and 15b in breast cancer cells, HIF-1α protein levels were not altered." (PMID 34445506, 2021). "In breast cancer cells, intracellular S100A7 was shown to form a complex with the cofactor Jab1, resulting in the translocation of Jab1 to the nucleus and its interaction with HIF-1a, resulting in the transcription of HIF-1a dependent genes." (PMID 34360919, 2021). "Similarly, sanguinarine promotes proteasomal degradation of HIF-1α via inactivating STAT3 under hypoxia and impedes the growth of breast cancer in vivo." (PMID 34575983, 2021). "Enhanced HIF1α inhibition was shown upon the combination treatment of palbociclib and TAS-116 in ASPC1 and HPAFII pancreatic cancer cell lines as well as SKBR3 and MDA-MB-361 breast cancer cells." (PMID 34686682, 2021). "We further analyzed published chromatin immunoprecipitation-coupled massive parallel DNA sequencing (ChIP-seq) data for the genome-wide transcriptional profile of HIF-1α and to identify candidate direct transcriptional activation targets of HIF-1α in breast cancer (GSE59935)." (PMID 34336836, 2021). "In brief, the reverse Warburg theory describes the glycolysis that occurs in CAFs by ROS, HIF1A, and nuclear factor-κB (NF-κB), resulting in lactate being released from CAFs by MCT4, which is then transported into the tumor cells by MCT1 in breast cancer, creating energy by mitochondrial OXPHOS." (PMID 34552932, 2021). "EGCG diminishes HIF-1α and VEGF levels in breast cancer cells." (PMID 34575983, 2021). "Moreover, ISL hampers breast cancer growth and the neoangiogenesis accompanying suppressed VEGF/VEGFR-2 signaling, which prompts HIF-1α proteasome degradation or directly blocks VEGF-2." (PMID 33401375, 2021). "Furthermore, ginsenoside Rg3 reduces HIF-1α expression to down-regulate SOX-2 and Bmi-1 expression levels, leading to decreased stemness and CSC features in breast cancer." (PMID 34769099, 2021). "Furthermore, it has been reported that hypoxia, by HIF1α, induces MMP2 expression in endothelial cells, cardiac fibroblasts, macrophages, and breast cancer cells." (PMID 34359789, 2021). "With the help of HIF-1α, which binds the HRE in the promoter of the PD-L1 gene, the expression of PD-L1 is significantly increased in many types of tumor cells, including melanoma, lung cancer, breast cancer, and prostate cancer cells." (PMID 33596985, 2021). "However, HIF‐1α expression is upregulated, and transcriptional activity is activated in TAM‐resistant human breast cancer cell lines, even under normoxic conditions." (PMID 34841716, 2021). "Under normoxic conditions, however, SIPA1 enhanced aerobic glycolysis without affecting the expression of HIF-1α and c-myc in breast cancer cells, suggesting additional mechanisms rather than HIF-1α/c-myc pathway are involved." (PMID 35096814, 2021).
breast cancer (continued). "Our findings provide evidence that hypoxia-responsive long non-coding MALAT1 could be transcriptionally activated by HIF-1α and HIF-2α, act as a miRNA sponge of miR-3064-5p, and promote tumor growth and migration in breast cancer cells." (PMID 34012919, 2021). "In addition, miR-100 delivered by MSC-Exos was able to inhibit angiogenesis in vitro by regulating the mTOR/HIF-1α/VEGF signaling axis in breast cancer cells, thereby influencing the behavior of breast cancer cells." (PMID 35186913, 2021). "HIF-1α binds to and transcriptionally activates JFK in hypoxic breast cancer cells, and analyses of public clinical datasets support the positive correlation between mRNA expression of JFK and HIF-1α in breast cancer." (PMID 34336836, 2021). "Additionally, we performed Western blot analysis to investigate the HIF-1α, CA IX and CA XII protein levels in the breast cancer cell lines HS578T, MDA-MB-231 and MCF-7 after treatment with the betulin sulfonamides under hypoxia." (PMID 34445506, 2021). "Specifically, in breast cancer stem cells, by absorbing endogenous miRNA let-7 and aborting let-7-mediated HIF1A mRNA suppression, hypoxia-induced H19 could stimulate HIF-1α expression." (PMID 32370770, 2020). "Moreover, XCL1 accentuated HIF-1α accumulation and ERK1/2 phosphorylation in this breast cancer cells." (PMID 33374849, 2020). "Similarly, TAM-secreted IL-6 activates the STAT3 pathway in breast cancer to upregulate TGF-β1 and hypoxia inducible factor 1-alpha (HIF-1α) gene expression during chemotherapy-induced apoptosis." (PMID 32326073, 2020). "Moreover, both hypoxia (via HIF-1α) and TGFβ signaling can independently stimulate the VEGF and CXCR4 expression to drive breast cancer bone metastases." (PMID 33489906, 2020). "In breast cancer cells, nanomaterials disassemble into their constituents (BBR and AgNPs) in the cell's cytoplasm, resulting in the downregulation of PI3K/AKT and Ras/Raf/ERK to hinder HIF-1α expression." (PMID 33521059, 2020). "Correlation analysis validated the negative correlation between Cav-1 and c-Myc expression levels (P = 0.001) as well as the negative correlation between Cav-1 and HIF1α expression levels (P = 0.018) in breast cancer patients." (PMID 32528105, 2020). "Specific activation of xanthine oxidase in MCF-7 human breast cancer cells also upregulated the level of oxidative burst, however it was not sufficient to induce HIF-1α accumulation." (PMID 33295886, 2020). "Studies have shown that HIF-1α could promoted the expression of VEGF-A 51, and it has been reported that SP1 could promote the expression of VEGF-C in breast cancer." (PMID 31892989, 2020). "PDK1, a HIF-1α target that antagonizes the function of PDH, a main rate-limiting enzyme for pyruvate converting to acetyl-coA and entering the TCA cycle, has been reported to be a critical regulator of breast cancer metabolism and metastasis." (PMID 33489906, 2020). "Increasing evidence has indicated that high levels of HIF-1α are likely indicative of poor clinical prognosis in breast cancer patients with lymph node-negative disease and invasive breast carcinoma." (PMID 33374849, 2020). "To assess the translational impact of the discoveries, we tested the relation between miRNA and HIF-1α expression using human breast cancer tissue and non-cancerous control tissues." (PMID 32707933, 2020). "Additionally, a positive correlation was determined between overexpression of hypoxia-inducible factor 1-alpha (HIF-1α) and DDX3 expression in breast cancer." (PMID 32512851, 2020). "Because CLDN6 attenuates hypoxia-induced tumour metastasis in a SUMOylation-dependent manner, these findings might provide a novel strategy for breast cancer treatment, and directly targeting SENP1/HIF-1α might prove to be a beneficial anti-cancer therapy." (PMID 32093760, 2020).